NRG4 (neuregulin 4)
Diseases named in the same sentence as NRG4 in open-access papers (continued):
Sharing a sentence is not in itself a finding about the gene and the disease.
Obesity (continued). "Finally, Nrg4 promotes a healthy adipokine profile during obesity." (PMID 28752050, 2017). "Finally, we found that Nrg4 promotes a beneficial adipokine profile during obesity." (PMID 28752050, 2017). "Neuregulin 4 (Nrg4) is a secreted adipokine recently identified as playing an important role in modulating systemic energy metabolism and in the development of metabolic disorders in rodent and human obesity, including type 2 diabetes and non-alcoholic fatty liver disease (NAFLD)." (PMID 27772531, 2016). "Overexpression of Nrg4 in the paraventricular nucleus (PVN) of the brain protects against HFD-induced obesity, whereas ErbB4 knockdown in oxytocin neurons accelerates obesity." (PMID 40243151, 2025). "Surprisingly, mRNA levels of Nrg-4 in WAT are low in humans and mice with obesity, and in humans with metabolic syndrome and obese children complicated by non-alcoholic fatty liver disease (NAFLD)." (PMID 39036605, 2024). "Nonetheless, circulating Nrg4 levels hold great potential in predicting the pathobiology of NAFLD in children and adults with obesity." (PMID 39162358, 2024). "Specifically, we sought to compare the levels of NRG4, FGF21, and irisin between metabolically healthy and unhealthy individuals with obesity." (PMID 39008201, 2024). "It has been shown that adipokines demonstrating protective effects, such as nesfatin-1 and neuregulin 4, often occur in elevated concentrations in metabolically healthy obesity (MHO) as compared to metabolically unhealthy obesity (MUO)." (PMID 38136166, 2023). "Nesfatin-1, neuregulin 4, myonectin, irisin, and brain-derived neurotrophic factor (BDNF) all seem to have protective effects against obesity." (PMID 38136166, 2023). "Nrg4 was revealed to activate adipose tissue angiogenesis in vivo and in vitro, and genetic deletion of Nrg4 can lead to reduced vascularity in BAT and WAT resulting in obesity even under a normal diet." (PMID 36703934, 2022). "Several recently discovered batokines, such as FGF21, NRG4, BMP8b, CXCL14, or adiponectin have been shown to exert a protective role against obesity by enhancing beiging of WAT, lipolysis, sympathetic innervation, or polarization of M2 macrophages." (PMID 34708041, 2021). "Neuroregulin 4 (NRG4), a ligand that specifically binds to ERBB4, has been reported to promote browning of white fat, fuel oxidation, prevention of high-fat diet-induced obesity, and improvement of insulin sensitivity." (PMID 31852448, 2019). "An intriguing aspect of Nrg4 regulation is that its expression in WAT is markedly downregulated in mouse and human obesity." (PMID 28752050, 2017). "Of note, individuals with MetS or metabolically unhealthy obesity had lower Nrg4 levels compared to those with metabolically healthy obesity without MetS." (PMID 39162358, 2024). "The purpose of this study was to evaluate the difference between the levels of NRG4, FGF21, and irisin secreted from brown adipose tissue between metabolically healthy and unhealthy individuals with obesity with equal amounts and distribution of adipose tissue." (PMID 39008201, 2024). "Our study aimed to research the correlation between obesity and serum BMP1, NRG4, and ApoA5 levels." (PMID 39280566, 2024). "As opposed to elevated Nrg4 levels, downregulation of Nrg4 expression in adipose tissue of mice and humans with unhealthy obesity compared to simple obesity is largely common." (PMID 39162358, 2024). "As with irisin and NRG4, FGF21 levels were higher in individuals with obesity suggesting that this increase could be a compensatory response or a result of resistance to FGF21." (PMID 39008201, 2024). "The purpose of the present study was to determine the levels of serum irisin, NRG4, and AMH in adolescents with obesity complicated with PCOS, compare these levels, and understand their correlation with other metabolic and hormonal parameters, as well as the influence of weight management on them." (PMID 34427289, 2021).
Obesity (continued). "In all, NRG-4 secreted by WAT may play a key role in preventing inflammation, and the decrease in its expression observed in obesity may exacerbate inflammation driven by infiltrated macrophages." (PMID 32655416, 2020). "Whereas Dai showed that circulating Nrg4 was not correlated with obesity indices, similar results were found by Zhang." (PMID 31815951, 2019). "Diet-induced obesity led to a significant decreased Nrg4 gene expression in WAT but not BAT in mice." (PMID 30766490, 2019). "Intriguingly, Wang’s study encapsulated a negative correlation between obesity and adipose Nrg4 mRNA, and Cai found that circulating Nrg4 was negatively associated with indices of obesity." (PMID 31815951, 2019). "NRG4 overexpression in obese mice did not affect pre-existing fat and body weight, but reduced chronic inflammation and improved obesity-related insulin resistance." (PMID 27184920, 2016). "Using the hydrodynamic gene transfer method, we demonstrate that Nrg4 gene transfer in mice suppressed the development of diet-induced obesity, but did not affect pre-existing adiposity and body weight in obese mice." (PMID 27184920, 2016). "Interestingly, Nrg4 levels were elevated in individuals with obesity compared to the subjects without obesity." (PMID 39162358, 2024). "However, studies continue to identify new adipokines and myokines, such as nesfatin-1, neuregulin 4, myonectin, irisin, BDNF, decorin, visfatin, and chemerin, which may participate in the development of obesity-related diseases." (PMID 38136166, 2023). "Interestingly, Nrg4 overexpression prevented obesity by reducing adipose tissue inflammation but did not affect pre-existing obesity and body weight." (PMID 36703934, 2022). "Also, the comparatively few studies investigating the relationships between NRG4 and cardiac function performed in humans have examined correlations between pathological states such as obesity, where NRG4 expression is diminished, and observed negative cardiometabolic health outcomes in such states." (PMID 40149686, 2025).
Insulin resistance (44 papers, 2015 to 2025). Increased resistance towards insulin, that is, diminished effectiveness of insulin in reducing blood glucose levels. "Neuregulin 4 (NRG4) is a novel metabolic regulator closely associated with insulin resistance and thyroid dysfunction." (PMID 40740865, 2025). "In both cross-sectional and case-control studies, it was reported that low serum Nrg4 levels were negatively associated with insulin resistance ‘HOMA-IR’ in women with GDM, suggesting an increased risk of T2DM." (PMID 39162358, 2024). "Previously, we described that 3T3-L1 adipocytes’ knockdown for Nrg4 expression (Nrg4 KD) results in dramatic insulin resistance, which is caused by a high expression of pro-inflammatory cytokines, leading to a reduction in insulin receptor expression." (PMID 39519269, 2024). "In this study, we searched for potential drivers of cell-autonomous inflammation and dysregulated autophagy associated with insulin resistance in Nrg4 KD adipocytes." (PMID 39519269, 2024). "Glucose-tolerance tests (GTTs) and insulin-tolerance tests (ITTs) revealed that Nrg4 deficiency exacerbated glucose intolerance and insulin resistance following HFD feeding at lower housing temperatures." (PMID 38015639, 2024). "Here, we observed that Nrg4 deficiency in adipocytes alters mitochondria and unbalances cellular energy metabolism, entailing harmful consequences that drive insulin resistance." (PMID 39519269, 2024). "In the current study we found that serum NRG4 was positively associated with insulin resistance and hsCRP (a marker of chronic low-level inflammation), but not with dyslipidemia or markers of liver injury in subjects without type 2 diabetes." (PMID 36187779, 2022). "Nrg4-deficient mice (Nrg4−/−) with more body weight developed more marked hepatic steatosis and insulin resistance compared with controls upon high-fat feeding." (PMID 32982804, 2020). "The association of circulating Nrg4 with subclinical atherosclerotic disease persisted after adjustment for metabolic risk factors, body fat, and insulin resistance." (PMID 27819316, 2016). "In summary, Nrg4 downregulation in adipocytes affects mitochondrial content and functioning, causing impaired cellular metabolism, which in turn results in oxidative stress, inflammation, and insulin resistance." (PMID 39519269, 2024). "On the other hand, this increase of neuregulin-4 might be a preventive mechanism for insulin resistance caused by the effect of GH." (PMID 37373801, 2023). "In our article, we focused only on selected ones—nesfatin-1, preptin, myonectin, omentin-1, gremlin-1, galectin-3, neuregulin-4, xenopsin-related peptide, xenin, neudesin, and lipocalin-2—and investigated their associations with insulin resistance in patients with PCOS." (PMID 35206286, 2022). "Here, we provided evidence supporting the essential role of Nrg4 as a beneficial adipokine whose deficiency leads to oxidative stress as a result of impaired metabolic homeostasis, probably initiated by dysfunctional mitochondria, which brings about severe insulin resistance." (PMID 39519269, 2024). "As a ligand, NRG4 predominantly activates the ErbB4 receptor, initiating ErbB3/ErbB4 signaling in hepatocytes and exerting protective effects against diet-induced insulin resistance and hepatic steatosis, partly by attenuating hepatic de novo lipogenesis." (PMID 40580113, 2025). "Strong evidence supports the role of BAT in alleviating insulin resistance, with NRG4 playing a pivotal role in enhancing glucose metabolism and reducing inflammation in metabolic tissues." (PMID 40149686, 2025). "Our findings indicate that, compared to T2DM alone, T2DM+FT patients exhibit significantly higher levels of HOMA-IR and NRG4 (P< 0.05), suggesting an exacerbation of insulin resistance and metabolic dysfunction." (PMID 40740865, 2025). "The yellow cluster identifies FGF21 as hepatoprotective, countering fetuin-A-induced insulin resistance, while NRG4 connects exercise to lipid oxidation." (PMID 40868109, 2025).
Insulin resistance (continued). "Overall, NRG4 is a brown fat-derived endocrine checkpoint that exhibits potently protective effects on metabolic disorders in animal models, including insulin resistance, hepatosteatosis, NASH, HCC, and atherosclerosis." (PMID 39872218, 2024). "Neuregulin 4 (Nrg4) is an adipokine that is highly expressed in brown adipose tissue (BAT) but also in white adipose tissue (WAT) that protects against insulin resistance." (PMID 39519269, 2024). "As mentioned, Nrg4 KD adipocytes showed marked insulin resistance characterized by enhanced expression of inflammatory cytokines and increased autophagic flux." (PMID 39519269, 2024). "Overall, the mitochondrial disturbances observed in Nrg4 KD adipocytes appear to be closely related to oxidative stress and insulin resistance." (PMID 39519269, 2024). "As expected, insulin-stimulated lipogenesis was completely blocked in Nrg4 KD adipocytes, in keeping with previous data on insulin resistance in this model." (PMID 39519269, 2024). "In 3T3-L1 adipocytes, the downregulation of Nrg4 expression enhances inflammation and autophagy, resulting in insulin resistance." (PMID 39519269, 2024). "Serum NRG4 levels are decreased in patients with non-alcoholic fatty liver, acute coronary syndrome, and metabolic disorders compared to control groups, and upregulation of NRG4 attenuates insulin resistance and decreases hepatic steatosis." (PMID 37174100, 2023). "TyG index was correlated, which has been proposed as a strong indicator of insulin resistance, and in our study, neuregulin-4 showed a significant positive correlation with TyG index in both whole group and separated group analyses." (PMID 37373801, 2023). "Neuregulin-4 (Nrg4) is an adipokine that exerts protective effects against metabolic disorders and insulin resistance." (PMID 36221104, 2022). "Abnormal serum levels of NRG4, AFM, and SERPINB1, as highly sensitive diagnostic tools, are closely related to insulin resistance in GDM patients." (PMID 36072413, 2022). "NRG4 has recently emerged as a brown fat-enriched secreted factor that ameliorates diet-induced metabolic disorders, including insulin resistance and hepatic steatosis." (PMID 36071032, 2022). "We therefore focused our attention on the mechanisms through which Nrg4 KD drives insulin resistance." (PMID 34884763, 2021). "Neuregulin 4 (Nrg4), another brown fat-enriched secreted factor, protects against diet-induced insulin resistance and hepatic steatosis." (PMID 34721298, 2021). "Future studies will have to delineate the Nrg4-induced mechanisms that allow to protect adipocytes from inflammation and deleterious autophagy in order to prevent insulin resistance." (PMID 34884763, 2021). "In that study, overexpression of hepatic NRG-4 ameliorated chronic inflammation, improved insulin resistance, and prevented HFD-induced weight gain and fatty liver." (PMID 32655416, 2020). "GDNF, CNTF, BDNF, and NRG4 improve insulin resistance and alleviate hepatic steatosis by reducing hepatic lipogenesis and improving β-oxidation." (PMID 32175323, 2020). "Neuregulin 4 (Nrg4) was recently identified as a brown fat-enriched secreted factor that ameliorates diet-induced metabolic disorders, including insulin resistance and hepatic steatosis." (PMID 28752050, 2017). "Nrg4 was recently identified as a brown fat-enriched endocrine factor that ameliorates HFD-induced insulin resistance and hepatic steatosis." (PMID 28752050, 2017). "Our results show that an increase of NRG4 expression inhibits diet-induced chronic inflammation, improves insulin resistance, and prevents weight gain in a diet-induced animal model." (PMID 27184920, 2016). "The results show that Nrg4 gene transfer protects mice from diet-induced weight gain and adiposity, and inhibits fatty liver and insulin resistance." (PMID 27184920, 2016). "It is speculated that the increase in circulating Nrg4 levels postpartum can be attributed to reduced insulin resistance." (PMID 39162358, 2024).
Insulin resistance (continued). "NRG4 depletion may lead to increased insulin resistance in adipocytes due to autophagy degradation of GLUT4 vesicules and inflammation." (PMID 39008201, 2024). "Apart from the inflammation, decreased Nrg4 levels could be the consequence of augmented dyslipidemia, oxidative stress, and insulin resistance." (PMID 39162358, 2024). "In addition, neuregulin-4 targets the liver, reducing diet-induced insulin resistance and hepatic lipogenesis." (PMID 37373801, 2023). "Importantly, another brown adipocyte enriched factor neuregulin 4 (Nrg4) has been demonstrated by the Lin laboratory to protect against diet-induced insulin resistance as well as hepatic steatosis in mice." (PMID 33953697, 2021). "Studies using NRG-4 null mice as well as adipose tissue-overexpressing NRG-4 mouse models demonstrated that NRG-4 protects against HFD-induced insulin resistance by attenuating hepatic de novo lipogenesis and activating mitochondrial fatty acid oxidation and ketogenesis." (PMID 32655416, 2020). "NRG-4 overexpression ameliorated insulin resistance by attenuating hepatic steatosis." (PMID 32655416, 2020). "Animal studies have shown that Nrg4 could prevent weight gain, attenuate diet-induced insulin resistance and hepatic steatosis through markedly mitigating hepatic lipogenic signaling, and maintain glycolipid balance." (PMID 32477429, 2020). "Ma demonstrated that up-regulation of Nrg4 could improve insulin resistance (IR) and prevent weight gain via Nrg4 gene transfer in mice." (PMID 31815951, 2019). "They explained that Nrg4 could stimulate insulin release from islet cells and improve insulin resistance under metabolic stress in mice." (PMID 31815951, 2019). "In the current study, adjustment for insulin resistance and body fat mass did not attenuate the association of circulating Nrg4 with increased CIMT and atherosclerotic plaque." (PMID 27819316, 2016). "Mice exhibiting low adipose Nrg4 expression tended to have more severe HFD-induced hyperglycemia and hyperinsulinemia, suggesting that reduced Nrg4 expression may be causally linked to insulin resistance." (PMID 28752050, 2017). "However, adjustment for insulin resistance and body fat mass did not attenuate the association of circulating Nrg4 with risk of MetS in the current study." (PMID 27772531, 2016). "Since LD is also characterized by insulin resistance, chronic low-grade inflammation, and MASLD, reduced NRG4 levels in our cohort likely reflect a metabolically adverse phenotype and may be attributable to the loss of functional AT, the primary site of NRG4 production." (PMID 40580113, 2025). "This study aims to explore the serum levels of neuregulin 4 (NRG4), afamin (AFM), and serpin family B member 1 (SERPINB1) in gestational diabetes mellitus (GDM) patients and their relationship with insulin resistance." (PMID 36072413, 2022). "In conclusion, serum Asprosin level increased and Nrg-4 level decreased in patients with CHD, which is closely related to glucose and lipid metabolism disorder and insulin resistance, and has certain significance for the prediction and diagnosis of T2DM with CHD." (PMID 36915073, 2023). "Moreover, Chi3l1 plays an important role in insulin resistance and diabetes, which closely correlates with glypican-4 (GPC-4), neuregulin-4 (NRG4), body mass index (BMI), the waist-to-hip ratio (WHR), and homeostasis model assessment of insulin resistance (HOMA-IR) in women with PCOS." (PMID 39769202, 2024). "Besides, brown adipocyte-derived Neuregulin 4 (Nrg4), a member of the epidermal growth factor (EGF) family of ligands, attenuates hepatic lipogenic signaling and protects mice against diet-induced insulin resistance and hepatic steatosis." (PMID 37465124, 2023).
Insulin resistance (continued). "In support of this, mice lacking Nrg4 developed more severe insulin resistance and hepatic steatosis following high-fat feeding, whereas fat-specific transgenic expression of Nrg4 significantly improves metabolic parameters and ameliorates diet-induced disruption of homeostasis." (PMID 28752050, 2017). "In addition to Nrg4, other potential BAT-enriched secreted factors that may affect insulin resistance and metabolic homeostasis need to be identified and studied." (PMID 26005433, 2015).